IFNG (interferon gamma)
Diseases named in the same sentence as IFNG in open-access papers (continued):
Sharing a sentence is not in itself a finding about the gene and the disease.
tumor (continued). "Consistently, blocking CXCL9 or IFNγ stimulates tumor growth in mice with myeloid SHP-2 deficiency." (PMID 38022587, 2023). "We speculated that the increased expression of IFNG might be caused by other components of non-tumor cells in the tumor microenvironment." (PMID 37154982, 2023). "The results revealed a strong correlation between CD64+ Mφ (CD64+CD68+) density and immune-activated pathways (e.g., IFNγ response, cytotoxic cells, antigen presentation signals) and a negative association with pro-tumor signals (e.g., TGFβ, Wnt, tumor proliferation signals)." (PMID 36879284, 2023). "IFNG, a gene encoding a kind of cytokine in the type II interferon family, is mainly expressed by immune system cells and plays a vital role in immune monitoring in the tumor microenvironment." (PMID 37154982, 2023). "Furthermore, prolonged exposure to IFNγ signalling, associated with tumor growth, has been shown to promote these immunosuppressive molecules, resulting in resistance to ICI therapy." (PMID 38026978, 2023). "However, in terms of antitumor immunity, low-risk patients scored significantly higher in HLA signature, CD8+ effector T cells, tumor antigen presentation, and interferon-gamma response than those high-risk ones." (PMID 37033959, 2023). "Given the predictive power of CD8+ T cell spatial localization, we observed abundant stroma-restricted CD8+ T cells with increased IFNγ expression in regions proximal to elevated tumor NOS2 expression, indicating a potential association between CD8+ T cells, IFNγ, and NOS2 regulation." (PMID 37169743, 2023). "Current studies have shown that the main factors influencing immunotherapy are: the tumor immune microenvironment, the tumor immunogenicity, the dysfunction of MHCs, irreversible T cell failure, and mutations in tumor genes including the interferon-gamma (IFN-γ) signaling pathway." (PMID 36759842, 2023). "Successful clinical response to immune checkpoint blockade has been linked with multiple features, such as IFNγ signatures, PD-1/PD-L1 expression, size and quantity of tumor-associated tertiary lymphoid organs, presence of B cells, and memory T cell phenotypes." (PMID 37388744, 2023). "Although still under investigation, OVT was shown to enhance antitumor immunity through the release of (i) tumor-associated antigens, (ii) pathogen-associated molecular patterns, and danger-associated molecular patterns, as well as (iii) cytokines (e.g., IFNγ, IL-12, and type-I IFNs)." (PMID 37623021, 2023). "Despite the well-established anti-proliferative effects of IFNs on tumor cells, our findings reveal novel facets of IFNγ signaling in tumor cells that may contribute to the pathogenic effects mediated by antitumor immunity, as seen in recent studies." (PMID 36900204, 2023). "Thus, tumor exposure resulted in close to 80% loss in the IFNγ generation capacity with about 30% of this loss being dependent on TIGIT/PVR engagement." (PMID 37345049, 2023). "Understanding the tumor‐promoting mechanisms and molecular targets of IFNγ is crucial to minimize its tumor‐promoting functions in IFNγ‐based therapies, and in cancer treatments associated with IFNγ increase." (PMID 37151134, 2023). "A more recent study demonstrated that a high density of tumour-infiltrating lymphocytes with positive T-bet transcription factor (Tbet + TILs) was associated with higher interferon-gamma (IFN-γ) levels both at baseline and following programmed cell death protein 1 (PD-1) blockade." (PMID 37816905, 2023). "Interestingly, tumor-associated activation of NF-κB represents a protective mechanism against IFNγ-mediated pathways." (PMID 37190141, 2023). "We next asked whether the IDO1-induced TRP loss in fact contributed to the anti-tumor effect of IFNγ." (PMID 36812891, 2023).
tumor (continued). "However, the present study reveals that CAP treatment enhances the expression of PD-1 and PD-L1 in T cells and tumor cells, respectively, but reduces the expression of T cell cytokines (IFNγ, GZMB, and IL-2) that are associated with CTL functions and activity." (PMID 37189453, 2023). "Conversely, though, elevated IFNγ at tumour sites has been implicated in immune evasion." (PMID 37752135, 2023). "We confirmed this dependence on IFNγ for stable tumor control using IFNγ-deficient mice." (PMID 36881506, 2023). "Among them are PD-L1 expression on the tumor as well as tumor-associated immune cells, the presence of a T-cell-inflamed tumor microenvironment signature or interferon-gamma signature, or a high mutational burden in the tumor cells as described in the “cancer immunogram”." (PMID 37444558, 2023). "Thus, mutations and deletions of IFNγ pathway-related proteins on tumor cells, such as IFNγ receptors and receptor chains, resulting in resistance to immunotherapy, which is a key factor of primary and acquired immune resistance." (PMID 36875059, 2023). "Tumours may also acquire mutations in JAK/STAT signalling pathways that mediate the response to IFNγ signalling, an important effector mechanism of the anticancer CD8 T-cell response." (PMID 37386922, 2023). "In contrast, IRI treatment caused an increase in IFNγ-producing tumor-infiltrating NK cells." (PMID 36397148, 2022). "Analysis of the mouse tumor chip data using Gene Ontology enrichment analysis of biological processes revealed that the triple combination upregulated genes associated with responses to interferon-gamma." (PMID 35058524, 2022). "Furthermore, heightening IFNγ-R1 expression levels on tumor cells increases the susceptibility to T cell-derived IFNγ, linking transcriptional IFNγ-dependent signaling in tumors to ICB therapy response." (PMID 35395848, 2022). "Furthermore, significant expression of BTN3A on MHC-II+ ovarian cancer-associated DC/macrophages was found to be associated with both inhibitions of the anti-tumor T cell response and production of proinflammatory cytokines, such as IL-2, IFNγ, and TNFα." (PMID 36362212, 2022). "We further hypothesized that tumor cell PA synthesis and/or transport gene set expression is associated with worse antitumor T-cell function as inferred by IFNγ or cytotoxic lymphocyte ssGSEA scores." (PMID 36052016, 2022). "Importantly, the Treg decrease was associated with higher CD8+ T cell infiltration into the tumours and a three-fold higher proportion of activated IFNγ+-producing T cells after N6L treatment." (PMID 36077801, 2022). "Indeed, loss of the receptor for IFNγ (IFNGR1) in tumor cells abrogated DuoBody-CD3x5T4–induced tumor cell kill." (PMID 36271507, 2022). "In light of these results, it was important to assess whether this hyperresponsiveness to IFNγ also alters how STUB1-deficient tumor cells respond to T cell attack." (PMID 35395848, 2022). "Notably, molecular analysis of isolated tumor-infiltrating leukocytes following NI-1701 administration revealed an upregulation of genes linked to immune activation, including IFNγ and IL-12b." (PMID 35538512, 2022). "Notably, we found that PD-L1 status was strongly associated with the degree of tumor-infiltrating lymphocytes, particularly T-cells that stained positive for IFNγ." (PMID 35155243, 2022). "To investigate the factor(s) that might cause differences in anti-tumor reactivities, we focused on case C177 because lymphocytes from four lymph nodes showed different reactivities in IFNγ production." (PMID 35606862, 2022). "IFNγ induces membrane-associated proteins on T cells that mediate tumor cell-in-cell formation." (PMID 36124553, 2022). "Interestingly, treatment with DX, MTX and OXP caused a significant increase in tumor-infiltrating CD8+ T cells expressing IFNγ." (PMID 36397148, 2022). "However, cancer cell-associated mechanisms often inhibit IFNγ production by suppressing CD8+ T-cell tumor trafficking, survival, and function." (PMID 34385592, 2022).
tumor (continued). "The nature of IFNγ-regulated tumor cell death may depend on specific underlying mechanisms, the partners of IFNγ, and tumor cell type in the tumor microenvironment." (PMID 34385592, 2022). "Loss of PBAF function increases tumor cell sensitivity to interferon-gamma, resulting in increased secretion of chemokines that recruit effector T cells, an increased percentage of dendritic cells and a higher ratio of tumor-inhibitory M1-like macrophages to tumor-promoting M2-like macrophages." (PMID 35928964, 2022). "CD8+ T cells isolated from highly glycolytic tumors with low glucose availability at TME had significantly lower rate of glycolysis, produced significantly less interferon gamma (IFNγ) and these exhaustive phenotypes were associated with faster tumor progression." (PMID 34359884, 2021). "Thus, depending on the effect of IFNγ exposure on malignant cells, these can be more or less susceptible to NK-cell induced tumor lysis." (PMID 33801234, 2021). "It has been previously shown that the presence of IFNγ in the TME could be directly associated with tumor virulence." (PMID 33514819, 2021). "Patients that did not respond to anti-CTLA-4 antibody ipilimumab therapy was reported to harbour mutations in the interferon gamma (IFN-γ) pathway genes leading to the ability of the tumour cells to escape from T cells, which was identified as a primary resistance to anti-CTLA-4 therapy." (PMID 34733591, 2021). "Thus, Th1 cells contribute either directly, by killing MHC-class II+ tumors, or indirectly, through IFNγ secretion, to boosting the anti-tumor function of innate immune cells such as M1 tumor-associated macrophages." (PMID 34073258, 2021). "Despite the lack of studies revealing a direct relevance between LUM and IFNG response, lumican plays a role in extracellular matrix remodeling, tumor-associated inflammatory response, and GBM resistance to TMZ, and perhaps is involved in the evasion of IFNG killing by GBM." (PMID 34566988, 2021). "Herein, the remarkable differences of lymphocyte-mediated immunity, interferon gamma signaling, and immune cell invasion between the high- and low-risk group further suggested that targeting tumor ferroptosis-linked metabolism through interferon gamma promotes the efficacy of immunotherapy." (PMID 34447410, 2021). "Expression of PD-L1 is upregulated in response to interferon-gamma (IFN-γ) signaling and responsiveness to PD-1 ICI is associated with preexisting IFN-γ-mediated immune activation that includes tumor-specific major histocompatibility complex (MHC) class II expression." (PMID 33418936, 2021). "To assess which factors present in the conditioned medium may regulate GITRL expression, we determined release of a panel of tumor-associated cytokines, namely TGFβ, IFNγ, IL-10, TNF and IL-2." (PMID 33538861, 2021). "In addition, GSVA analysis of macrophages revealed that pathways associated with anti-tumor (e.g., Interferon-gamma (IFN-gamma) and Interferon-alpha (IFN-alpha)) response pathways were enriched in NACT-ESCC." (PMID 34697289, 2021). "Systemically, the sustained presence of elevated cytokines that can drive tumor immune surveillance such as IL-1044, GM-CSF, IL-12, and IFNγ was intrinsically associated with early onset and sustained tumor engraftment of highly activated CD8+ T cells, including bifunctional IFNγ and TNFα producers." (PMID 34446712, 2021). "Therefore, dysfunction of the HLA-I antigen processing pathway (HLA-I APP) or the IFNγ response pathway in tumor cells has been identified as a frequent cause of both primary and acquired resistance to ICIs, often correlating with worse prognosis." (PMID 34458148, 2021). "Besides, IFNγ stimulation significantly reduced VEGF secretion in tumor-associated fibroblasts, leaving the angiogenesis further inhibited." (PMID 34476218, 2021).
tumor (continued). "In summary, TNFRSF9, TNF, and IFNG represent an efficient and effective surrogate combination for a much broader panel of functions associated to tumor-reactivity, and can potentially identify the majority of the tumor-specific reactive TIL repertoire in situ." (PMID 34707600, 2021). "The deficiency of IFNGR1 causes tumor cells to be unresponsive to IFNγ and promotes tumor growth." (PMID 35127816, 2021). "Indeed, Hif1a specific deletion in NK cells drives tumor rejection in NK cell-sensitive solid tumor models, and it is associated with increased NK cell activation in terms of IFNγ production and cytoxicity." (PMID 33546248, 2021). "Smoking may increase the mutational load, leading to neoantigen expression in tumor cells and helping to maintain an inflammatory environment, resulting in interferon gamma (IFNγ)-driven expression of PD-L1." (PMID 32795913, 2020). "In another study, mice deficient in IFNγ, a cytokine that is critical for innate and adaptive immunity, received tumor-localized irradiation and demonstrated decreased expression of MHC-I and CXCL9/CXCL10, which are important chemoattractants for cytotoxic T cells." (PMID 33050580, 2020). "We also show changes in DCs, where Siah2 loss increased expression of the IFNγ-induced chemokine Cxcl9, which recruits effector T cells to a tumor site, and concomitantly decreased expression of Ccl17 and Ccl22, chemokines that contribute to recruitment of Tregs to tumors." (PMID 31911617, 2020). "Thus, it appears that YAP activity in tumor-infiltrating CD8 cells is uniquely linked to the pro-inflammatory IFNγ response." (PMID 32322254, 2020). "Interestingly, these unique DEGs are annotated with GO biological process terms associated with IFNγ regulation and secretion (GO:0032609), IL-13 secretion (GO:0030101), and immune response to tumor cell (GO:0002418)." (PMID 32093192, 2020). "In conclusion, our findings established an effective five‐IFNγ response‐related mRNA‐based risk score, which has the potential to be a novel prognostic signature and which may provide insight into tumor immune microenvironments of SKCM affliction." (PMID 32902917, 2020). "In summary, this study employed an isogenic murine system with subsequent validation in multiple patient cohorts to demonstrate that PBRM1 loss decreases IFNγ dependent signaling and tumor immunogenicity, and suggest that PBRM1 mutation associates with ICB resistance." (PMID 32358509, 2020). "Indeed, PTPN2 deletion in B16 tumor cells enhanced IFNγ signaling, caused a strong change in the expression profile of IFNγ response gene, and increased phosphorylation of STAT1, thereby reducing tumor growth of PTPN2-null mice." (PMID 33003469, 2020). "Two types of PD-L1 expression in the tumour are known: an innate mechanism induced by genetic mutation and an adaptive mechanism induced by the stimulation of inflammatory cytokine, the latter of which is primarily caused by IFNγ." (PMID 31914969, 2020). "Additionally, the tumor cells with Atrx deficiency were more easily to be damaged by T cells under IFNγ stimulation." (PMID 33409155, 2020). "Tumor-associated endothelial cells may release interferon-γ (IFNγ) that upregulates PD-L1 expression to inhibit the anti-tumor activity of T-cells." (PMID 33256070, 2020). "Mechanisms of acquired resistance to ICBT have been discovered through tumor tissue sequencing performed pre-and post-treatment, and currently, most evidence points to mutations in tumor cells that affect the IFNγ signaling pathways, antigen expression, and antigen presentation complexes." (PMID 32380703, 2020). "IL-17A production can dismantle the anti-tumor functionality of IFNγ-producing γδ T cells, and Tγδ17 cells have been associated with tumor progression and poor outcomes in multiple tumor types; however, the mechanism by which this occurs in humans is not fully understood." (PMID 33255339, 2020).
tumor (continued). "Additionally, MCPyV TAg-specific cells gated on CD3+CD4+TNFα+ cells were polyfunctional for IL-2 and the Th1 effector molecules granzyme B, IFNγ, and TNFα, a feature associated with immune-mediated tumor clearance." (PMID 33362774, 2020). "Although mechanisms linking elevated LDH to poor prognosis are incompletely understood, LDH-associated lactic acid may impede interferon-gamma production by tumor-infiltrating T-cells and NK cells thus interfering with immune-mediated tumor control." (PMID 33202676, 2020). "Mechanistically, we demonstrate that the synergistic effect of tankyrase and checkpoint inhibitor treatment is dependent on loss of β-catenin in the tumor cells, anti-PD-1-stimulated infiltration of T cells into the tumor and induction of an IFNγ- and CD8+ T cell-mediated anti-tumor immune response." (PMID 32332858, 2020). "High IFNγ levels are associated to anti-tumor responses and a pro-inflammatory microenvironment." (PMID 32733470, 2020). "While replicating in vivo in the tumor, G47Δ-IL12 treatment causes increased local production of IL-12 in the tumor, which is accompanied by a marked release of downstream Th1 mediator interferon gamma (IFN-γ) in the tumors and, to a lesser extent, in the blood." (PMID 32050597, 2020). "These autoreactive T-cells may recognize self-antigens expressed on TET tumor cells, causing IFNγ release, which in turn upregulates PD-L1 expression on TET tumor cells." (PMID 33260538, 2020). "The co-expression of PD-L1 and PD-L2 on myeloid infiltrating cells suggests that expression of both proteins may be induced in the same manner, for instance by IFNG signaling, while expression on tumor cells might be caused by different mechanisms." (PMID 33424844, 2020). "However, we observed a trend toward increased PD-L1 expression in tumor cells (CD45−) and tumor-associated leukocytes (CD45+) consistent with activation of IFNγ signaling in anti-PD-1-treated animals." (PMID 32051401, 2020). "IFNγ is associated with anti-proliferative and anti-tumor mechanisms but also may have pro-tumor activities (downregulating MHC, upregulating PDL1) and clinical studies have had limited success." (PMID 32575843, 2020). "IFNγ is associated with an antitumor role via extrinsic or tumor cell intrinsic mechanism." (PMID 31113461, 2019). "Interestingly, the ability of Folfox to synergize with anti-PD-1 therapy was directly associated with the Folfox-driven induction of IFNγ-producing CD8 T cells as well as of enhanced PD-L1 expression on tumor cells in vivo." (PMID 31191545, 2019). "This suggests that the absence of PD-L1 expression on tumor cells in TC0/IC3 samples may be caused by impaired IFNγ signaling in these tumor cells." (PMID 31125352, 2019). "Increases in PD-L1 expression can occur on SCC cells as a result of mutations in tumor cell signaling pathways or exposure of tumor cells to inflammatory cytokines IL-1, IL-6, GM-CSF, IFNγ, TNFα, and VEGF and the gamma-chain cytokines IL-2, IL-7, IL-10, IL-15, and IL-21." (PMID 31554151, 2019). "We found an association between the IFNγ T-cell response upon stimulation with tumor-specific HPV16 E6 peptides and PD-1 blockade, and lower levels of aTregs as well as elevated levels of a particular subset of CD8+ T cells, specifically CD8+FoxP3+CD25+ T cells." (PMID 30755279, 2019). "There are some pro-inflammatory factors in the tumor microenvironment reported to extend neutrophil survival time such as the interferon gamma (INFγ), and activate tumor-associated neutrophils in different conditions, which results in anti-tumor and pro-tumor functions of neutrophils." (PMID 31010242, 2019). "Therefore, we next measured the production of the effector cytokines IFNγ and TNFα by tumor-associated CD8+ and CD4+ T cells in our involution group tumors." (PMID 31244852, 2019). "The lack of correlation between PD-L1 TC and IC expression in this subgroup may be caused by impaired IFNγ signaling in tumor cells." (PMID 31125352, 2019).